MIR4523 (microRNA 4523)
Synonyms: hsa-mir-4523
Gene: MicroRNA gene on chromosome 17 (29,390,662 to 29,390,730, forward strand). Ensembl gene ENSG00000284162.
Homologues: Orthologues: chimpanzee MIR4523 (100% identical).